CD4 (CD4 molecule)
Diseases named in the same sentence as CD4 in open-access papers (continued):
Sharing a sentence is not in itself a finding about the gene and the disease.
tumor (continued). "More interestingly, the CD4 T cells from the HLA-DR.B1-matched donors are also able to kill the peptide-pulsed autologous DCs and more importantly, a tumor cell line, MDA-MB-231, expressing a high level of cyclin D1." (PMID 19707583, 2009). "This would then lead to CD4+ T cell recognition and ultimately tumor destruction by immune effector cells such as CTL and NK T cells." (PMID 20016802, 2009). "Recently, it has been indicated that CD4+ Th cells play a crucial role in tumour immunology in addition to CD8+ CTL in both animal and human systems." (PMID 19277034, 2009). "Results from these two approaches well confirmed the importance of tumor-shed PGE2 in impairment of IL2Rγc survival signal in CD4+ T cells that culminated to apoptosis." (PMID 19812686, 2009). "In 5 of 9 patients, tumor reactive CD4+/CD8+ T-lymphocytes increased significantly, indicating specific anti-tumor immunity." (PMID 19216794, 2009). "In our experimental model, we observed a marked decrease in the surface expression as well as total amount of IL2Rγ chain in CD4+ T cells that were co-incubated with tumor supernatants." (PMID 19812686, 2009). "The numbers of CD3+ CD4+ T cells and the CD4+/CD8+ ratios in peripheral blood were consistently lower in the tumor-bearing mice than in the normal mice (P < 0.05)." (PMID 19570195, 2009). "It was interesting to note that theaflavins, the black tea polyphenols, protected IL2Rγc signaling in CD4+ T cells from tumor-secreted PGE2 insult by inhibiting Cox-2 expression and subsequent PGE2 release from tumor cells." (PMID 19812686, 2009). "In order for CD4+ T cells to recognize these Ags/peptides, they must first be processed by APCs or tumor cells, loaded onto the HLA class II dimer, and transported to the cell surface." (PMID 20016802, 2009). "Current paradigms suggest that CD4+ T cells play critical roles in the optimal induction and maintenance of clinically beneficial tumor immunity." (PMID 19812686, 2009). "In the second case, two Vβ-receptor sequences were found by RT-PCR (Mouse ID-10) and surface phenotyping of DP CD4+CD8+ tumor cells showed staining with corresponding Vβ-specific monoclonal antibodies." (PMID 20046882, 2009). "Although CD4+ T cells are central to the function of the immune system, their role in tumor immunity remains under-appreciated." (PMID 19812686, 2009). "Although no definitive mechanisms are provided for the therapeutic efficacy of CD4 T cell in this case, the study demonstrated the important role of CD4 T cells in anti-tumor immunity in a patient with cancer." (PMID 19707583, 2009). "One is the requirement of CD4+ T cells for the induction of natural killer cells and inhibition of tumor through IFN-γ production by T cells and IFN-γ receptor expression." (PMID 19788747, 2009). "The present study confirms the decrease in the ratio of CD4+/CD8+ with increasing tumor burden, which appeared to result mainly from a decrease in CD4+ T cells and an increase in CD8+ T cells." (PMID 19570195, 2009). "The tumours were infiltrated by large numbers of CD4+ and CD8+ effector cells, and an increase in INF-γ was noted." (PMID 19384299, 2009). "Cell surface expression of T cell markers was found to vary between tumor samples, though the majority expressed both CD4 and CD8." (PMID 19688092, 2009). "Analysis of data revealed that PGE2 present in cell free tumor supernatant interferes with one of the major pathways for survival and activation of CD4+ T cells." (PMID 19812686, 2009). "TIL frequency also increased during tumor growth, with a decline in the relative proportion of CD4+ T cells among the TIL population." (PMID 19226468, 2009). "Our studies suggest a possible role of CD4 T cells in anti-tumor immunity as cytotoxic effectors against HLA-DR expressing cancers and provide a rationale for designing peptide vaccines that include CD4 epitopes." (PMID 19707583, 2009).
tumor (continued). "Several immunological blood parameters such as serum IL-2, INF-alpha, INF-gamma, and CD4/CD8 ratio were examined after the tumor disappearance, but all were within the normal range (data not shown)." (PMID 19830126, 2009). "Perturbation in phospho-Stat-5 nuclear translocation activity was also observed in tumor-exposed CD4+ T cells in comparison to its untreated counterparts." (PMID 19812686, 2009). "In such protective immunity, CD8+ T cells played a major role in the response to TAP-negative tumor cells, while CD4+ T cells had a significant role as well." (PMID 19629186, 2009). "Recently, we investigated the quality of the anti-tumor CD4+ T cell responses in PC patients undergoing surgical resection, by comparing the anti-carcinoembryonic (CEA) and anti-viral CD4+ T cell immunity." (PMID 19798410, 2009). "In five out of nine patients, specific tumor reactive CD4/CD8 + T lymphocytes were found in PBMC by the IFN-γ secretion assay, demonstrating that i.p. trAb therapy is able to induce a verifiable increase of autologous tumor reactive T lymphocytes." (PMID 19216794, 2009). "Before reaching the tolerance or tumour escape a therapeutic vaccine must elicit a strong cellular immune response involving the CD4 and CD8 stimulation." (PMID 19473517, 2009). "Our studies provided the proof of concept that CD4 T cells can be cytotoxic against MHC class II positive tumor cells." (PMID 19707583, 2009). "By contrast, these tumor cells were more heterogeneous in terms of the surface expression of the CD4 and CD8 markers." (PMID 20011522, 2009). "CD4+CD25+ Treg depletion by administration of anti-CD25 antibodies in mice produced a significant increase in anti-tumour activity, along with an increased incidence of autoimmune diseases." (PMID 19384299, 2009). "In the first approach, when CD4+ T cells were cultured in presence of supernatants of tumor cells pre-treated with celecoxib or tranfected with Cox-2-siRNA." (PMID 19812686, 2009). "DCs/tumor fusions are potent inducers of antigen-specific polyclonal CD4+ T cells, which are essential for the induction of augmented polyclonal CTL responses against autologous tumor cells." (PMID 20182533, 2009). "Immunological reactivity was tested by analyzing PBMC for specific tumor reactive CD4+/CD8+ T lymphocytes using an IFN-γ secretion assay." (PMID 19216794, 2009). "Depletion of CD8+ T cells blocked the anti-tumor effect of Con A whereas depletion of CD4+ T cells also partially affected the Con A anti-tumor activity." (PMID 19272170, 2009). "We have also reported that soluble factors derived from tumor cells promoted the generation of CD4+ CD25high Foxp3+ Treg and inhibited CTL induction by fusions." (PMID 20182533, 2009). "More importantly, the peptide DR-1 can induce cytotoxicity of CD4 T cells against tumor cells highly expressing cyclin D1 in the context of HLA-DR.B1 molecules." (PMID 19707583, 2009). "Similar to the results for MHC class I, the expression of MHC class II in tumor epithelium was positively associated with various T cell markers, including CD3, CD4, CD8, CD45RO, TIA-1, Granzyme B, CD25 and FoxP3." (PMID 19641607, 2009). "In a model of tumor recurrence the CD8+ T cell-mediated immunosurveillance was suppressed by IL-13 producing CD1d-restricted CD4+ T cells." (PMID 19968878, 2009). "The antitumor response elicited by the vaccines is dependent on CD4+ T cell activation through HLA class II molecules on both APCs and tumor cells." (PMID 20016802, 2009). "Further support towards the involvement of PGE2 comes from the results that (a) purified synthetic PGE2 induces CD4+ T cell apoptosis, and (b) when knocked out by small interfering RNA, cyclooxygenase-2 (Cox-2)-defective tumor cells fail to initiate death." (PMID 19812686, 2009). "IFN-γ is secreted from activated cells such as Th1 CD4+ T-helper cells into the tumor microenvironment." (PMID 19228418, 2009).
tumor (continued). "Rejection of tumor was also observed when the activation of iNKT cells by yet unidentified tumor-derived ligands fostered a CD4+ and CD8+ adaptive immune response." (PMID 19968878, 2009). "One particular murine in vivo study suggests that conversion of naïve CD4+ T cells into antigen-specific iTregs takes place within the tumour microenvironment, and is driven by the tumour itself." (PMID 19384299, 2009). "Our study demonstrated the presence of Cox-2 derived PGE2 in tumor supernatant and that the effect of tumor supernatant on CD4+ T cells bore remarkable similarities with the effects of PGE2 exposure on these cells." (PMID 19812686, 2009). "Antibody-mediated blockade of CTLA-4 signaling can augment antigen-specific CD8 T cell responses in a CD4-independent manner, promoting anti-tumor and autoimmune effects." (PMID 19247441, 2009). "The authors showed that IL-2 administration inhibited tumour growth and prolonged survival and that both CD8 and CD4 lymphocytes were required for tumour regression." (PMID 19935800, 2009). "A recent study has provided a clear evidence that CD4 T cells can be more powerful anti-tumor effectors than CD 8 T cells, in a mouse model." (PMID 19707583, 2009). "The present study was designed to determine the potential mechanisms of tumor-derived PGE2 leading to CD4+ T cell apoptosis." (PMID 19812686, 2009). "CD4+CD25HI regulatory T (Treg) cells directly suppress the activation of anti-tumor effector T cells in a contact-dependent manner." (PMID 18334033, 2008). "Rather, the CD8/CD4 ratio and CD4/8 status appear to be critical for anti-tumour immunity, and infiltrating Treg correlates with both of these measures of anti-tumour immune function in OSCC." (PMID 18349839, 2008). "Cognate immune reactions against tumor cells depend on a balance between activated tumor antigen specific CD4+ and CD8+ T cells and suppressive regulatory T cells." (PMID 18334033, 2008). "Autoantibodies to NY-ESO-1 were associated with increased tumor-infiltrating CD8+, CD4+ and FoxP3+ cells." (PMID 18923710, 2008). "Given this information, we examined the effect of Rapamycin-resistant CD8+ and CD4+ T-cells on Wnt-1 tumor growth in vivo." (PMID 18570671, 2008). "In the unlikely event that CD4+CD25high regulatory T cells expand into tumor/effector cells or simply become broadly immunosuppressive, there needs to be a way to eliminate them from the body." (PMID 19046457, 2008). "Among the many cell types which play a role in tumor eradication, type 1 CD4+ Th1 and CD8+ Tc1 lymphocytes (T1 cells) which secrete high levels of IFN-γ are proposed to be most relevant." (PMID 18570671, 2008). "Expressed by activated dendritic cells, IL23 has anti-tumor effects through inducing CD4+ T-cell proliferation and its anti-tumor effects are reportedly to be inhibited by the depletion of CD4+ or CD8+ subset." (PMID 18485203, 2008). "Increased tumor infiltrating CD4+ T cells following treatment with Ad-Flt3L and Ad-TK was only inhibited when PC61 was administered on day 24 (p>0.05)." (PMID 18431473, 2008). "Tumour-associated macrophages CD68+ were positively correlated with tumour CD4+ (P<0.01) and CD8+ (P<0.001) T lymphocytes." (PMID 18797461, 2008). "The total number of CD45+ tumor infiltrating immune cells increased 10 d after intratumoral delivery of Ad-Flt3L and Ad-TK (p<0.001), as did the numbers of CD4+ T cells (p<0.001) and CD8a+ T cells (p<0.001)." (PMID 18431473, 2008). "While the importance of CD4+ T cells for productive tumour immune responses has just begun to be fully discovered their role in the induction of autoimmune responses has long been acknowledged." (PMID 18350151, 2008). "We explain the decreasing CD4+/CD8+ ratio as predominantly due to a decrease of CD4+ T cells as the tumor progresses." (PMID 17338814, 2007). "Many studies in mouse models indicate that CD4+CD25+regulatory T cells (Treg) significantly impact the development of anti-tumour immune responses." (PMID 17294404, 2007).
tumor (continued). "Although most EBV-associated tumors express MHC II, the low number of tumor cells undergoing lytic replication in vivo challenges the concept of an analogous role of virion-specific CD4+ T cells in tumor control." (PMID 17611619, 2007). "We have examined the requirement for CD4+ T cells in the generation of anti-tumour immune memory following PDT." (PMID 17505510, 2007). "We first found a significant enrichment of CD4+FOXP3+ Tregs in tumours developing in vivo, where approximately half of total CD4+ TIL were FOXP3+." (PMID 17565340, 2007). "Collectively these data indicate that CD4+CD25+ Treg inhibit innate immune responses that are capable of tumour rejection in both B6 and RAG–/– mice." (PMID 17294404, 2007). "Depletion of CD4+ cells by treatment with anti-CD4 antibodies will also result in depletion of T helper cells and regulatory T cells, which are CD4+ and have been shown to suppress anti-tumour immunity." (PMID 17505510, 2007). "Lungs from mice bearing 4-day established pulmonary metastases were obtained 24 hours after adoptive transfer of tumor-specific T cells and frozen sections were stained with mAbs against CD4, CD8, NK1.1, Mac-1, and GR-1." (PMID 18001476, 2007). "Although another study showed that Treg can inhibit NK killing of tumours using unstimulated CD4+CD25+ cells, we only observed inhibition of NK cell killing when the CD4+CD25+ cells were stimulated with anti-CD3 Ab and irradiated APC." (PMID 17294404, 2007). "Following in vitro activation these T cells contained a significantly elevated frequency of tumor-specific CD4 and CD8 T cells with augmented function in vitro and therapeutic efficacy in vivo." (PMID 17868452, 2007). "We did however observe that IFNγ−/− mice, when challenged with MCA, demonstrate a reduction of the percentage of CD4+FOXP3+ Tregs within tumours and TDLN." (PMID 17565340, 2007). "While vaccination-induced tumor regression was abolished in mice depleted of CD4 T cells, both CD4 and CD8 cells were needed to adoptively transfer immunity to naïve mice." (PMID 16725035, 2006). "We have demonstrated the ability of a single immunization to inhibit tumor growth in a CD4+ T cell dependent manner and the need for both CD4 and CD8 T cells to adoptively transfer immunity." (PMID 16725035, 2006). "In adoptive immunotherapy of cancer, CD4+ T-cells were also shown to play an essential role by providing early stimuli for proliferation of tumor-reactive T-cells." (PMID 17118192, 2006). "Precisely, murine IFN-γ produced by either CD4+ or CD8+ cells inhibits tumour-induced angiogenesis in syngeneic tumour models." (PMID 16721359, 2006). "In the presence of a relatively high level of CD4+ T-cell infiltration, patients with a sufficient number of tumour-infiltrating CD8+ T cells demonstrated a significantly better prognosis." (PMID 16421594, 2006). "Compared with the diluent-treated control group, the CCL19-treated CC-10 TAg mice showed significant increases in the frequency of CD4 (20%), CD8 (50%) and CD11c+DEC205+ DC (70%) and a decrease in CD4+CD25+ Treg (20%) cells at the tumour site." (PMID 16598185, 2006). "Recent studies implicate CD4+CD25+ regulatory T cells (TREG) within the tumour microenvironment in suppression of CD4+ and CD8+ T-cell activation and proliferation." (PMID 17024127, 2006). "There was a modest decrease in the frequency of CD4+CD25+ Treg population at the tumour site following CCL19 therapy." (PMID 16598185, 2006). "Tumour-infiltrating lymphocytes were both of the CD4 and CD8 subsets and the majority presented an activated CD69+ phenotype." (PMID 16641897, 2006). "A decreased percentage tumour volume of CD4+ T-lymphocytes (P=0.025) and an elevated C-reactive protein (P<0.001) were also associated with poorer cancer-specific survival." (PMID 15700032, 2005). "There was an inverse relationship between percentage tumour CD4+ T-lymphocytes and C-reactive protein (rs=−0.245, P=0.003)." (PMID 15700032, 2005).
tumor (continued). "The process of lymphocyte infiltration and anti-tumour activity is also influenced by the differential activity of helper (CD4+) T lymphocyte subsets and local cytokine profiles." (PMID 15890075, 2005). "There was a positive relationship between percentage tumour CD4+ and CD8+ T-lymphocytes (rs=0.440, P<0.001)." (PMID 15700032, 2005). "The CD8+ T cell survival and activity against the most of the tumor is increased by CD4+ T helper cells (CD4+CD25-) and downregulated by CD4+ T regulator cells (CD4+CD25+)." (PMID 16188028, 2005). "The CD4+CD25+ T cells maintain an microenvironment in the tumor sites that conceal the immunogenicity of tumor to permit progressive growth of antigenic tumors." (PMID 16188028, 2005). "The identification of CD4+CD25+ TR cells provided a new way to study relationship between tumor development and immune suppression." (PMID 15679891, 2005). "To investigate the possible reason that the proportion increased in spleen lymphocytes of tumor-bearing mice, we analyzed the CD4+CD25+ and total CD4+ cells in spleen lymphocytes." (PMID 15679891, 2005). "This is often accompanied by poor or non-expression of co-stimulatory molecules, which not only limits clonal expansion of tumor-specific CD4+ T cells, but also hinders the production of cytokines, and the development of CTL." (PMID 16045800, 2005). "Despite extensive in vitro proliferation in response to antigen-independent stimulation for 85 days, 1.5 × 107 CD4 cells retained efficacy against 3-day s.c.tumors, with 3/5 mice achieving complete tumor regression (P = 0.019 versus control)." (PMID 15566571, 2004). "This represents another crucial step in the development of an antigen-specific immune response, prior to the interaction of primed cytotoxic (CD8+) and helper (CD4+) T cells with the tumour cells." (PMID 15298707, 2004). "CD4+ T-cell help is required during the generation and maintenance of effective anti-tumour CD8+ T cell-mediated immunity." (PMID 15054451, 2004). "This indicates that maintenance of CD4+ as well as CD8+ tumor-reactive effector T cells would be required for optimal adoptive immunotherapy against disseminated metastatic disease." (PMID 15566571, 2004). "CD4+ T cell anti-tumor function is mediated through cross-presentation of specific tumor-antigens by tumor associated APC." (PMID 15566571, 2004). "Here, we isolated tumor-sensitized T cells and activated them in vitro using conditions that led to greater than 108-fold numerical hyperexpansion of either the CD4+ or CD8+ subset while retaining their capacity for in vivo therapeutic efficacy." (PMID 15566571, 2004). "In contrast to CD8+ T cells, CD4+ T cells recognise tumour-specific antigenic peptides on MHC class II molecules via an exogenous processing pathway." (PMID 14583778, 2003). "Taken together, it is strongly suggested that OK-432 plus IL-2 stimulation induces autologous tumour-reactive CD4+ Th1 killer lymphocytes." (PMID 14612896, 2003). "Expression of B7 family members in murine tumour models has been shown to activate CD8+ T cells and/or CD4+ T cells against tumour cells." (PMID 12865933, 2003). "Previous work has shown that CD8+ T cells are responsible for rejection of E.G7-OVA tumours and that administration of an anti-CD4 monoclonal antibody, that mediates regression of established E.G7-OVA tumours, leads to increased infiltration of CD8+ cells." (PMID 12671716, 2003). "The relevance of tumour cells as APC for CD4+ cells appears to be dependent on the coexpression of MHC II and accessory molecules such as the invariant chain (Ii) and HLA-DM, each of which are under the primary control of CIITA, the Class II transactivator." (PMID 12569387, 2003).